FAM209A (family with sequence similarity 209 member A)
Description:
May play a role in sperm acrosome biogenesis.
Synonyms: C20orf106; dJ1153D9.3
Tractability: Antibody: UniProt predicts a signal peptide or a membrane-spanning region.
Gene: Protein-coding gene on chromosome 20 (56,517,187 to 56,526,152, forward strand). Ensembl gene ENSG00000124103.
Subcellular location: Nucleus inner membrane
Subcellular location (Human Protein Atlas): Cell Junctions; Plasma membrane
Gene Ontology:
Molecular function: protein binding
Cellular component: extracellular exosome; nucleus; nuclear inner membrane
Genetic constraint (gnomAD): Loss-of-function variants: 7 observed, 12.16 expected, observed/expected ratio (o/e) 0.58, 90% interval 0.33 to 1.08. The synonymous counts are far from expectation, so gnomAD's model fits this gene poorly and the ratio says little. Missense variants: 205 observed, 216.33 expected, observed/expected ratio (o/e) 0.95, 90% interval 0.85 to 1.06. Synonymous variants: 55 observed, 76.9 expected, observed/expected ratio (o/e) 0.72, 90% interval 0.57 to 0.89.
Homologues: Orthologues: chimpanzee FAM209A (96% identical), pig FAM209B (64% identical), mouse Fam209 (61% identical), rat Fam209 (61% identical). Paralogues in human: FAM209B (88% identical).